LCN2 (lipocalin 2)
Diseases named in the same sentence as LCN2 in open-access papers (continued):
Sharing a sentence is not in itself a finding about the gene and the disease.
breast carcinoma (continued). "Interestingly, in human breast cancer, LCN2 levels have been found to be elevated at advanced cancer stages." (PMID 32575507, 2020). "LCN2 can activate the malignant properties of breast cancer cells." (PMID 31151292, 2019). "It was reported that LCN2 promoted breast cancer progression by inducing epithelial to mesenchymal transition (EMT) through the ERα/Slug axis and might represent a biomarker of breast cancer." (PMID 32047513, 2019). "CHI3L1 and LCN2, two immune-related biomarkers used for monitoring intraductal tumor progression and breast cancer patient prognosis, confirmed the differential tumor progression and immunology with differential levels in spleens, primary tumors and serum of both models." (PMID 31921184, 2019). "For verification of the mammary tumor disease progression either with or without additional macrophages, two immune-related proteins CHI3L1 and LCN2, which both have been identified as prognostic biomarkers in breast cancer patients, were incorporated in the current study." (PMID 30111338, 2018). "Consistently, elevated expressions of MCT2 as well as β-hydroxybutyrate-induced genes, IL-1β and LCN2, are significantly (P values: MCT2/IL-1β=0.029; MCT2/LCN2=0.017, log-rank test) correlated with poor prognosis in breast cancer patients in two independent cohorts." (PMID 28281525, 2017). "Furthermore, the expressions of IL-1β and LCN2 were also induced in breast cancer cells co-culture with MGDAs." (PMID 28281525, 2017). "Furthermore, the expressions of IL-1β and LCN2 mRNA were positively correlated with MCT2 expression in breast cancer specimens." (PMID 28281525, 2017). "The impact of Lcn-2 on metastasis might depend on the cellular source, with at least macrophage-derived Lcn2 promoting metastasis in mammary carcinoma." (PMID 28979267, 2017). "For instance, the fourth most upregulated gene, lipocalin 2, has also been reported to be oncogenic in both lung and breast cancers and could be stimulated by interferon-γ and tumor necrosis factor-α in murine subcutaneous adipocytes." (PMID 28629450, 2017). "Furthermore, the significant correlation between MCT2 and IL-1β/LCN2 expressions in clinical breast cancer specimens supports the role of an MCT2-mediated oncogenic pathway in breast cancer progression." (PMID 28281525, 2017). "Moreover, inflammatory cytokines, such as interleukin (IL)-6, induce LCN2 expression depending on activation of the STAT3 signaling pathway, IL-1β and the tumor cell-derived factor IL-10 also promote LCN2 expression in lung and breast cancer." (PMID 27912767, 2016). "Recent studies have reported increased LCN2 expression in various human pathologies, including kidney diseases and obesity, as well as solid tumors and other cancers, such as leukemia, breast cancer, intrahepatic cholangiocarcinoma and liver cancer." (PMID 26840566, 2016). "Furthermore, several studies have also shown that LCN2 is present in the urine of patients with breast cancer and in tissue homogenates from gastric cancer patients." (PMID 27602760, 2016). "Lcn2 promotes breast cancer progression and is overexpressed in a variety of tumours." (PMID 26512722, 2015). "In breast cancer, LCN2 is upregulated by the HER2/PI3K/AKT/NF-κB pathway." (PMID 25940797, 2015). "Furthermore, the presence of LCN2-MMP-9 complexes has been found in the urine of breast cancer patients and in tissue homogenates of gastric cancer patients." (PMID 23056397, 2012). "Our results suggested that lipocalin 2 was a key modulator for breast cancer cells metastasis." (PMID 19077278, 2008). "Gene expression data from the microarray analysis of 92 primary breast tumors (from the UNC Microarray Database) were analyzed for expression of the six genes (CEACAM6, CDH1, CST6, ESR1, LCN2, and SCNN1A) whose loss characterizes the hypermethylator phenotype among breast cancer cell lines." (PMID 18221536, 2008).
breast carcinoma (continued). "This study demonstrated that lipocalin 2 overexpression could increase cell migration, invasion, and lung metastasis in 4T1 murine breast cancer cells." (PMID 19077278, 2008). "Lipocalin 2 was overexpressed in the metastatic 4T1 murine mammary cancer cells." (PMID 19077278, 2008). "Besides that, cell lines derived from highly metastatic breast cancer, such as MDA-MB-231, expressed and secreted higher amounts of NGAL/lipocalin 2 than cell lines derived from benign, organ defined breast cancers." (PMID 19077278, 2008). "Mice deficient in LCN2 or treated with an LCN2 inhibitory monoclonal antibody shown a reduction in tumor growth and metastasis, attributed to the destabilization of the LCN2/MMP-9 complex, underscoring the potential of such interventions in addressing breast cancer brain metastasis." (PMID 39188682, 2024). "Recent studies have found that LCN2 expression significantly elevates VEGF levels by inducing hypoxia-inducible factor 1 (HIF-1α) expression through the extracellular signal-regulated kinase (Erk) pathway in both MCF-7 human breast cancer cells and an angiogenic line derived from MDA-MB-436 cells." (PMID 39188682, 2024). "Finally, core biopsies of 652 breast cancer patients undergoing neoadjuvant chemotherapy, examined via immunohistochemistry, revealed that the intensity and expression of Lcn-2 were significantly related to estrogen and progesterone receptor status, as well as with the histological tumor type." (PMID 37958332, 2023). "High levels of LCN2 could predict the poor prognosis of patients with breast cancer." (PMID 36834846, 2023). "Hence, this provides further evidence that blocking Lcn-2 could be considered a novel strategy for breast cancer therapy." (PMID 37958332, 2023). "In conclusion, our results suggest that dissimilarly expression of few mediator encoding genes ANPTl7, MMP3, S100A8, LCN2 ESM1 in primary versus distant metastasis organs and their prognostic and predictive scores in breast cancer cohort may be a helpful to predict future metastasis." (PMID 34072157, 2021). "Moreover, TAMs could also increase the release of IRPs, such as the paracrine factor lipocalin 2 (Lcn2), to serve as an iron donor and promote the progression of breast cancer cells." (PMID 34796174, 2021). "Hence, knockdown of Lcn2 in breast cancer cells can make it an ideal anti-angiogenic target." (PMID 33916786, 2021). "Finally, a study of breast cancer showed that overexpression of LCN2 in 4T1-H-Ras-transformed cells (4T1-R) reverted the mesenchymal phenotype of the 4T1-R cells to a more epithelial phenotype by increasing E-cadherin, reducing vimentin, and suppressing cell invasion." (PMID 32575507, 2020). "LCN2 is a glycoprotein released by various cells of the organism, including epithelial cells, macrophages, neutrophils and tumor cells, and this protein can be found in plasma, serum, and urine in different clinical situations, including metastasis of breast cancer or colon cancer." (PMID 31151292, 2019). "However, LCN2 is a potential therapeutic target for breast cancer metastasis." (PMID 30871117, 2019). "Furthermore, local and systemic levels of CHI3L1 and LCN2, two immune-related biomarkers used for prognosticating and monitoring disease in breast cancer patients and mice, provided an additional verification of the tumor progression in 4T1 inoculated mice with and without RAW264.7 macrophages." (PMID 30111338, 2018). "However, it remains to be investigated whether LCN1 might exert tumor-promoting functions like its family member LCN2 known to induce epithelial to mesenchymal transition and to promote breast cancer invasion in an ERα-dependent manner." (PMID 28482871, 2017). "Furthermore, either MGDAs co-culture or treatment of β-hydroxybutyrate, an intrinsic histone deacetylase (HDAC) inhibitor, increases histone H3K9 acetylation and induces expressions of IL-1β and LCN2 to enhance tumorigenicity in MCT2-expressing breast cancer cells." (PMID 28281525, 2017).
breast carcinoma (continued). "Additionally, LCN2 is a novel regulator of angiogenesis in human breast cancer." (PMID 25476483, 2015). "Chronic nicotine exposure induces neutrophil recruitment in the lung, where neutrophils release LCN2, promoting MET in tumor cells, thereby enhancing their colonization and metastatic potential in breast cancer." (PMID 40564191, 2025). "For breast cancer normal-tumor differentiation, CXCL14, MSLN, LCN2, and MED1 emerged as significant predictors, supported by evidence of their differential expression and involvement in tumor progression." (PMID 41139924, 2025). "Suppression of primary mammary tumor formation has also been reported in MMTV-PyMT129 and MMTV-PyMTB6 mouse models with different LCN2 defects." (PMID 40109857, 2025). "In human breast cancer, the MMP-9 x LCN2 complex was first identified by antibody detection and has been found in the urine of breast cancer patients as opposed to healthy individuals." (PMID 39188682, 2024). "RGS10 reduced breast cancer cell proliferation, colony formation, invasion, and migration by inhibiting EMT via a novel mechanism dependent on LCN2 and MIR539-5p." (PMID 39145770, 2024). "Tumor stroma-derived LCN2, particularly that secreted by M2 macrophages via STAT3 and C/EBPβ signaling pathways, induces EMT in MCF-7 breast cancer cells, thereby enhancing their migration and invasion capabilities in both in vitro and in vivo models." (PMID 39188682, 2024). "Prior research indicates that the downregulation of LCN2 and MMP-9 can significantly suppress breast cancer migration and invasion." (PMID 39188682, 2024). "Of the tumor-intrinsic gene response, we previously discovered that co-culture with MSCs upregulated LCN2, an iron sequestering protein, and CD44, a marker of stem-like cells, in breast cancer cells." (PMID 39480488, 2024). "Our results show that GDF5, BAHCC1, LCN2, FGF14-AS2, and IDH2 are among the top five most effective mRNAs involved in lymph node metastasis of breast cancer based on their SHAP values." (PMID 39150915, 2024). "This increased expression of Lcn-2 further upregulated the invasion and migration capacity of different estrogen receptor α (ERA+) breast cancer cells, such as BT-474, MCF-7, ZR-75-1, and T-47D." (PMID 37958332, 2023). "Actually, LCN2 has the potential to preserve MMP-9 activity by preventing its degradation, and there is a close relationship between LCN2 expression and MMP-9 activity in a mouse model of breast cancer." (PMID 36798684, 2023). "For instance, using the well-established polyomavirus middle T antigen (MMTV-PyMT) breast carcinoma model, it was shown that crossing MMTV-PyMT mice with Lcn-2−/− mice resulted in a decreased tumor onset and burden compared to wild-type MMTV-PyMT mice." (PMID 37958332, 2023). "LCN2 expression levels are elevated in various human diseases and several cancers, including breast cancer, by inducing the EMT in breast cancer cells." (PMID 34072157, 2021). "Others have also found that reduction of LCN2 levels affected the same features in MDA‐MB‐231 cells (TNBC cell line) and in SK‐BR‐3 (HER2+ breast cancer cell line)." (PMID 34342930, 2021). "LCN2 promotes EMT by upregulating mesenchymal markers such as fibronectin and vimentin in breast cancer cells while inhibiting the epithelial marker E-cadherin." (PMID 34588926, 2021). "Lcn2 protein abnormal expression initiates the epithelial-to-mesenchymal transition (EMT) process, cell migration and invasion, and angiogenesis in breast cancer." (PMID 33916786, 2021). "When cultured with breast cancer cell lines, macrophages upregulate SLC40A1 and LCN2 to acquire an iron-releasing phenotype to support cancer proliferation." (PMID 34389031, 2021). "As proof of principle and to substantiate the role of Lcn-2-bound iron in the tumor context, we established a 3D tumor spheroid model using stable Lcn-2R knockdown MCF-7 and MDA-MB-231 breast cancer cells." (PMID 33808732, 2021).
breast carcinoma (continued). "Here, they formulated liposomes modified with anti-CXCR4 antibodies on the surface, encapsulating Lcn2 siRNA for targeting MBC cells and for blocking the migration along CXCR4-CXCL12 axis in breast cancer." (PMID 33916786, 2021). "LCN2 plays a role in promoting cell migration and invasion of MCF-7 breast cancer cells by inducing EMT." (PMID 33123472, 2020). "LCN2 is reported to induce the production of HIF-1α and VEGF in breast cancer cells to stimulate angiogenesis, via the ERK signaling pathway." (PMID 33123472, 2020). "LCN2 is reported to contribute to cardiovascular and kidney fibrosis and promote epithelial-to-mesenchymal transition (EMT) in breast cancers." (PMID 33292361, 2020). "Because breast cancer stages II–III are characterized by extravasation to lymph nodes and distant organs, high levels of LCN2 seem to promote the invasive potential of breast cancer cells." (PMID 32575507, 2020). "LCN2, whose expression is most upregulated (37.2 fold more compared to control) in shZRF1 MCF7 cells, was shown to promote breast cancer progression in vitro and in vivo, and it contributes particularly to early events of metastasis." (PMID 29983888, 2018). "In mice with breast cancer, the oncogene HER (for human epidermal growth factor receptor) induces LCN2 expression and antibody-mediated blockade by trastuzumab antagonizes this effect." (PMID 30534534, 2018). "Conversely, a decrease in LCN2 expression significantly reduces the invasion and migration abilities of HER2-positive breast cancer cells." (PMID 26840566, 2016). "LCN2 has also been demonstrated to be up-regulated in human OSCC and in pancreatic, colon, skin, and breast cancers in humans; knockdown of LCN2 inhibits the growth and invasiveness of prostate cancer cells." (PMID 25635769, 2015). "Conversely, decrease in LCN2 expression significantly reduces the invasion and migration abilities of HER2-positive breast cancer cells." (PMID 25940797, 2015). "Preoperative serum levels of lipocalin-2 and MMP-9 were measured in 303 breast cancer patients and 74 healthy controls recruited between 2004 and 2007." (PMID 22640376, 2012). "The cooperative role between lipocalin-2 and MMP-9 in breast cancer progression prompted us to investigate the concomitant presence of MMP-9 and we found the positive correlation between lipocalin-2 and MMP-9 in serum from breast cancer patients." (PMID 22640376, 2012). "Moreover, LCN2 expression is negatively regulated by estrogen receptor alpha (ERα) in an NFAT3-dependent manner, inhibiting the migration of breast cancer cells." (PMID 40109857, 2025). "On the other hand, the LCN2 level does not decrease during the progression of breast cancer, myeloproliferative neoplasms, skin squamous cell carcinoma, gastric carcinoma, esophageal squamous cell carcinoma, or thyroid cancer." (PMID 40109857, 2025). "Previous studies have shown that MCF-7 breast cancer cells, which naturally produce MMP-9, stably transfected to express LCN2, form tumors in xenograft models characterized by enhanced tumor growth, proliferation, and microvessel density compared to wild-type MCF-7 tumors expressing MMP-9 only." (PMID 40732340, 2025). "Similar results were obtained when HER2+ SKBR3 breast cancer cells were treated with Herceptin to block HER2, and a reduction in LCN2 expression was observed, suggesting that LCN2 may be a downstream target of the HER2 pathway." (PMID 40732340, 2025). "Similarly, LCN2, which exhibits a widespread presence in diverse tissue types, has been identified as a key player in facilitating breast cancer cell proliferation and migration via the nuclear factor of activated T-cells (NFAT1)-LCN2-TWEAK signaling cascade." (PMID 40369189, 2025). "MSLN has been validated as a novel immunotherapy target for triple negative breast cancer, while LCN2’s role in promoting breast cancer progression and metastasis has been well-documented." (PMID 41139924, 2025).
breast carcinoma (continued). "Clinical studies have further corroborated this interaction, suggesting that LCN2 could serve as a predictive biomarker for MMP-9 levels and the progression of breast cancer." (PMID 39188682, 2024). "Studies have shown that LCN2 is actively involved in these processes by promoting cellular proliferation, angiogenesis, EMT and ECM remodeling, thereby enhancing the metastatic potential of breast cancer cells." (PMID 39188682, 2024). "Lcn2 potentiated VEGF-induced angiogenesis in vivo and may promote tumor progression by inducing breast cancer angiogenesis." (PMID 37222464, 2023). "HIC1 expression has been found to be silenced only in triple-negative breast cancer compared with other breast cancer molecular subtypes, and HIC1 slicing could facilitate triple-negative breast cancer progression by targeting lipocalin-2 (LCN2)." (PMID 37388742, 2023). "A relationship between other markers of poor breast carcinoma prognosis, such as progesterone receptor (PR)- and estrogen receptor (ER)-negative status and Lcn-2, has been reported in primary breast carcinoma." (PMID 37958332, 2023). "Compared with normal non-cancer and breast cancer patients, patients with colorectal or pancreatic cancer had significantly higher levels of circulating LCN2." (PMID 36428623, 2022). "They observed that LCN2 secreted from macrophages in response to IL-10 induces cellular growth and proliferation of MCF-7 breast cancer cells, suggesting that macrophage-derived LCN2s might contribute to tumor development and progression." (PMID 35470375, 2022). "LCN2 also correlates with several important unfavorable prognostic factors in breast cancer, such as hormone‐negative status, high proliferation levels, high histologic grade, and the presence of lymph node metastases." (PMID 34342930, 2021). "This can imply that OCT targeting can result in higher accumulation of Lcn2 siRNA in the breast cancer cells as compare to the non-targeted liposomes." (PMID 33916786, 2021). "Moreover, PTEN inhibits metastasis in breast cancer cells through the downregulation of WNT1 inducible signaling pathway protein 1 (WISP1) and lipocalin-2 (LCN2), and inactivation of NFkB signaling in non-small cell lung cancer cells." (PMID 32986377, 2020). "In particular, FPN is not the only route of iron secretion by M2-like TAMs, as its knockdown did not alter iron levels in breast cancer cells, but also, LCN2 expression mediates iron secretion by macrophages in the tumor microenvironment." (PMID 33287315, 2020). "Importantly, both LCN2 and FABP1 are detectable in primary breast cancer patient samples (respectively)." (PMID 31105883, 2019). "Mining transcriptome data from Py8119 and Py230 cells revealed a lipocalin 2 (LCN2) axis that is selectively expressed in the metastatic Py230 cells, predicts poor breast cancer patient survival and is elevated in circulating serum of mice chronically treated with conditioned media from Py230 cells." (PMID 31105883, 2019). "LCN2 regulates hypoxia-inducible factor 1 (HIF-1) through signal-regulated kinase ERK, and the vascular endothelial growth factor (VEGF) mediated by HIF-1 regulates breast cancer angiogenesis." (PMID 29789480, 2018). "Lipocalin-2 (LCN2), which is a member of the lipocalin family and functions to ligate ferric siderophore-like molecules, is involved in various cancers including lung cancer, breast cancer, ovarian cancer, colon cancer and pancreatic cancer." (PMID 25476483, 2015). "However, no other prior studies have examined the relationship between the circulating level of lipocalin-2 and MMP-9 and their combined effects on the prognosis of breast cancer." (PMID 22640376, 2012). "LCN2 has been shown to inhibit tumor angiogenesis by suppressing RAS-induced VEGF expression in 4 T1 tumor cells, but to increase angiogenesis in a different breast cancer model." (PMID 22559235, 2012).